EGFR (epidermal growth factor receptor)
Diseases named in the same sentence as EGFR in open-access papers (continued):
Sharing a sentence is not in itself a finding about the gene and the disease.
lung cancer (continued). "Our in vitro experiments showed that Met treatment resulted in the selection of A549 lung cancer cells that expressed increased levels of wild type EGFR on the cell surface (EGFRhigh)." (PMID 29312591, 2017). "Greater success has been seen in studies of the EGFR mutant lung cancer population in the setting of acquired EGFR kinase resistance, and those that select for MET activation (e.g. amplification, high copy number, mutations)." (PMID 29050231, 2017). "Daily dosing with Gefitinib can cause the initial regression of tumors in most patients with primary EGFR mutant lung cancer." (PMID 29069801, 2017). "In conclusion, this study has provided evidence of the clinical validity and utility of a RT-PCR and a MS test for the detection of EGFR gene mutations that predict the prognosis and clinical benefits of EGFR-TKI treatment in lung cancer patients." (PMID 29254176, 2017). "In this study, we report the ability of Met to enrich human lung cancer cells expressing higher levels of wild type EGFR (EGFRhigh) and enhance their sensitivity to the therapeutic effect of the TKR inhibitor, Erlo." (PMID 29312591, 2017). "To improve the efficacy of lung cancer treatments, we aimed to identify the compounds that can disrupt Src-EGFR cooperation and are less dependent on EGFR status than other compounds." (PMID 29132432, 2017). "Quantitative RT-PCR confirmed the EGFR-mediated expression of 16 microRNAs, including previously reported miRNAs (e.g. miR-130b, miR-200a and miR-222) identified in Calu-1 lung cancer cells.." (PMID 28703807, 2017). "For example, HER3 has been shown to mediate resistance to the EGFR inhibitor gefitinib in both breast and lung cancer cells." (PMID 28881753, 2017). "In this study, we confirm the relationship between EGFR activation and LysRS s207 phosphorylation, and its role as a prognostic factor in lung cancer after primary surgery." (PMID 29029422, 2017). "Based on preclinical data, combination trials of CB-839 with EGFR inhibitors in EGFR mutant lung cancer and with proteasome inhibitors in multiple myeloma are now being planned." (PMID 29212209, 2017). "Copy number gain of oncogenes including EGFR, KRAS and c-MYC has been reported in lung carcinoma, where it was associated with advanced stage and poor clinical outcome." (PMID 28501852, 2017). "Clinical data confirm the important connection between MCT-1 activity and YY1, EGFR and MnSOD, as well as the development of malignant microenvironments in lung carcinoma." (PMID 28394354, 2017). "In vitro tests on cellular uptake were performed on fluorescently labeled GE11-PLGA/PEG–PLGA nanoparticles in incubation with A549 cells, a human lung carcinoma cell line overexpressing EGFR." (PMID 29271876, 2017). "EGFR monoclonal antibodies are tumor specific and react with breast and lung carcinomas and malignant gliomas." (PMID 28427241, 2017). "Collectively, our study provides a novel approach to overcome EGFR-TKI resistance using cetuximab modified MP-SiO2 NP, which holds strong potential for effective management of EGFR-mutant lung cancer." (PMID 27151505, 2016). "HUVEC cells were co-cultured with EGFR transfected A549 stable lung cancer cells in a trans-well system for 3 days." (PMID 27362942, 2016). "The median content of the mutant EGFR DNA in all lung cancer tissues tested was 9.41% (95% CI: 7.38–15.44)." (PMID 27368002, 2016). "Significantly increased migration and invasion were observed in both exon 19 deletion and exon 21 L858R missense mutant EGFR genes transfected lung cancer cells." (PMID 27362942, 2016). "Lung cancer patients harboring the EGFR exon 19 deletion achieve longer survival following treatment with gefitinib or erlotinib, as compared to those with tumors harboring the L858R point mutation." (PMID 27081078, 2016). "After transfection with the MIIP plasmid, steady-state EGFR protein expression was downregulated to about 30% of that in control cells in the three lung cancer cell lines used." (PMID 26824318, 2016).
lung cancer (continued). "It appears that some types of oncogenes regulate lung cancer progression or suppression, such as EGFR or ALK." (PMID 27542716, 2016). "Other preclinical studies have shown that treatment with platinum drugs and cetuximab in combination with gefitinib in colon and lung cancer cells resulted in antagonistic effects because of inhibition of chemotherapy-induced ROS by EGFR-targeted agents." (PMID 26719345, 2016). "Higher expressions of CDH5 protein and mRNA in lung cancer stable cells transfected with exon 19 deletion EGFR gene compared to wild type EGFR gene transfected stable cells were observed." (PMID 27362942, 2016). "Specifically, we demonstrated that GPR171, also known as platelet-activating receptor H963, is a tumor-promoting gene that induces proliferation, invasion, and migration of lung cancer cells in an EGFR-independent manner." (PMID 26760963, 2016). "To determine if GPR171 exerts its tumor-promoting activity via an EGFR-dependent pathway, we compared GPR171 expression patterns with EGFR phosphorylation patterns (p-EGFR) in 47 lung cancer specimens using immunohistochemistry." (PMID 26760963, 2016). "In the present study, we have established an in vivo imaging LMC model of EGFR-mutant lung cancer and demonstrated that third generation EGFR-TKI, AZD9291, can manage LMC in our model." (PMID 26716903, 2016). "The use of EBUS-TBNA as an initial method for tissue acquisition and EGFR testing in lung cancer patients is increasing." (PMID 27685950, 2016). "We therefore demonstrated that the activation of PI3K/AKT pathway was independent on the EGFR signaling in the lung cancer stem cells." (PMID 27690301, 2016). "Mutation detection of DNA extracted from CTC-enriched samples demonstrated activating mutations in the EGFR, KRAS, and AR genes in patients suffering from lung cancer, colorectal cancer (CRC), and castration-resistant prostate cancer (CRPC) respectively." (PMID 26980749, 2016). "Increased migration and invasion abilities were also noted in the mutant EGFR genes transfected lung cancer cells in our study." (PMID 27362942, 2016). "It is a representative marker and abnormal expression of EGFR influences the treatment and prognosis of lung cancer." (PMID 27827952, 2016). "We also present an analysis of the role of cfDNA as a liquid biopsy technique and NGS as an analytical tool in studying EGFR and MET, two frequently mutated genes in lung cancer." (PMID 27589834, 2016). "Crosstalk between EGFR and MET has been implicated in therapeutic resistance to EGFR inhibitors in colon and lung cancers." (PMID 27655711, 2016). "In this study, we found that treatment with AT-101 in combination with gefitinib significantly inhibited cell proliferation, as well as promoted apoptosis of EGFR TKIs resistant lung cancer cells." (PMID 27431492, 2016). "The results of the compassionate-use program of afatinib indicate that this drug is equally effective in EGFR-mutant lung cancer patients with CNS metastasis compared with the patients without CNS metastasis." (PMID 26716903, 2016). "EMT is also a mechanism by which EGFR mutant lung cancer cells become resistant to erlotinib therapy." (PMID 26654942, 2016). "Global phosphoproteome (phospho-Ser/Thr/Tyr) profiling showed that ablation of TBK1 expression in KRAS mutant lung cancers leads to compensatory activation of a panel of receptor tyrosine kinases including EGFR and MET." (PMID 28154798, 2016). "We identified 25D3 status as a novel host factor that influences the growth of EGFR mutant lung cancer and discovered that 25D3 signaling persists despite dramatic reduction in CYP27B1 expression and 1αOHase activity." (PMID 26654942, 2016). "Studies were designed by us to establish the effects of 25D3 on gene regulation and growth of EGFR mutant lung cancer in vitro and in vivo." (PMID 26654942, 2016). "We observed that EGFR protein was decreased in lung cancer cells by MIIP overexpression and increased by MIIP knockdown." (PMID 26824318, 2016).
lung cancer (continued). "The challenge of clinical tumor resistance remains a major bottleneck to meaningfully impact long term survival outcome of precision therapy in EGFR-mutant lung cancer." (PMID 27852038, 2016). "Strikingly, we found that the combination of cisplatin and hyperthermia significantly decreased the EGFR protein level in EGFR mutant-driven lung cancer cells." (PMID 26654941, 2016). "Our data showed that this modified nano-medicine can overcome EGFR-TKI resistance and holds therapeutic implication for effective management of EGFR-mutant lung cancer." (PMID 27151505, 2016). "The study further clarifies the impact of first-line erlotinib in EGFR mutant lung cancer in Caucasian patients." (PMID 27032107, 2016). "In lung cancer, exosomal EGFR protein levels have been postulated as a biomarker for lung cancer diagnosis." (PMID 27285987, 2016). "The association of EGFR mutations and CDH5 expression was studied in lung cancer cells using western blot analysis." (PMID 27362942, 2016). "TOPK dictates the responsiveness of lung cancers to the EGFR-targeted TKI gefitinib through the transcription factor AP-1 component c-Jun." (PMID 26745678, 2016). "The heterogeneous pattern of EMT is also a feature of primary lung cancers and cell lines driven by other oncogenes such as EGFR or K-Ras, likely reflecting a multilayer complexity in the regulation of EMT in cancer." (PMID 27119231, 2016). "Further inhibition of the Akt pathway showed decreased expression of CDH5 in EGFR mutant lung cancer cells." (PMID 27362942, 2016). "To establish an LMC model with an EGFR-mutant lung cancer, we utilized the human EGFR mutant lung adenocarcinoma PC-9/ffluc (exon 19 deletion), HCC827/luc, and H1975/luc cells, which were transfected with the fusion gene of luciferase for in vivo imaging." (PMID 26716903, 2016). "Here we design a cetuximab-capped mesoporous silica nanoparticle (MP-SiO2 NP) as the drug carrier to specifically target EGFR-mutant lung cancer cells and efficiently release loaded drugs including doxorubicin and gefitinib." (PMID 27151505, 2016). "Here we showed that DbA induced the up-regulation of CAR10 and EGFR and its downstream signaling molecules through the induction of the FoxF2-YB-1 signal cascade, contributing to lung cancer cell proliferation in vitro and in vivo." (PMID 27322209, 2016). "In this study, we investigate the correlation between EGFR mutations and cadherin-5 (CDH5), which is an angiogenic factor, in lung cancer cells." (PMID 27362942, 2016). "Based on these molecular characteristics, we assumed this lung cancer to be responsive to an EGFR-TKI." (PMID 27548442, 2016). "It has been reported that epidermal growth factor receptor tyrosine kinase inhibitors (EGFR-TKIs) had the active response in brain metastasis of lung cancer." (PMID 26805738, 2016). "LMR was found to be a prognostic factor in small cell lung cancer, in early-stage NSCLC patients post operation, in advanced lung cancer treated with cytotoxic chemotherapies, and in EGFR-mutant lung cancer patients treated with first-line EGFR-TKIs." (PMID 27821111, 2016). "In conclusion, we have established an LMC model for EGFR-mutant lung cancer and demonstrated the potential of third generation EGFR-TKI AZD9291, on not only EGFR-TKI naïve LMC but also EGFR-TKI-refractory LMC." (PMID 26716903, 2016). "The researchers revealed that the expression of Notch‐1 was upregulated in EGFR‐TKISs developed resistant lung cancer cells." (PMID 27770511, 2016). "The activation of EGFR with the treatment of EGF in lung cancer cells was positively correlated with the phosphorylation of TOPK." (PMID 26745678, 2016). "Acquired resistance is a bottleneck that restricts the efficacy of epidermal growth factor receptor-tyrosine kinase inhibitor (EGFR-TKI) for lung cancer." (PMID 27655708, 2016).
lung cancer (continued). "Although Erlotinib and Geffitinib have shown great success in shrinking kinase domain mutant EGFR positive lung cancers, resistance to EGFR-targeted therapy is almost an inevitable obstacle in the clinic." (PMID 26654941, 2016). "EGFR monoclonal antibodies have been applied as efficacious adjuvant treatments in solid tumors, such as colon and lung cancer." (PMID 27438047, 2016). "In summary, we seek to elucidate a novel immune-mechanism of EGFR inhibitor-induced skin rash and corresponding anti-tumor immunity in lung cancer." (PMID 27467256, 2016). "Human lung cancer cell line H1975 was employed and the phosphorylation of EGFR and its downstream molecular proteins AKT and ERK1/2 were investigated to verify the inhibitory role of cordycepin." (PMID 27689974, 2016). "Metformin has been demonstrated to sensitize EGFR tyrosine kinase inhibitor (TKI)-resistant lung cancer cells by reversing the EMT and decreasing IL-6 signaling activation." (PMID 27519177, 2016). "In future, small molecule TOPK inhibitors should be developed to enhance lung cancer treatment efficacy with EGFR-TKIs." (PMID 26745678, 2016). "Here we compare persister-derived, erlotinib-resistant colonies that arose from a single, EGFR-addicted lung cancer cell." (PMID 26891683, 2016). "We present a case of multiple primary lung cancer(MPLC) displaying heterogeneous EGFR and PTEN molecular profiles." (PMID 27823967, 2016). "Leptomeningeal carcinomatosis (LMC) remarkably decreases the quality of life of EGFR-mutant lung cancer patients." (PMID 26716903, 2016). "Several groups have examined the lung cancer chemopreventive efficacies of EGFR TKIs gefitinib and erlotinib in different preclinical models." (PMID 27458163, 2016). "Flexibility and capacity of assessing multiple targets in one run make NGS a valuable tool taking into account the fact that not only EGFR but other genes are emerging as potential targets in lung cancer management." (PMID 27215400, 2016). "The antiangiogenic role of another MEK inhibitor, Selumetinib, was previously reported in lung cancer cells resistant to anti-EGFR therapies." (PMID 27429047, 2016). "Current guidelines for lung cancer treatment with EGFR tyrosine kinase inhibitors (TKI) include only patients with mutated EGFR, although some patients with wildtype EGFR (wt-EGFR) have exhibited positive responses to this therapy as well." (PMID 26646697, 2016). "Previous studies have suggested that PTEN loss contributes to erlotinib resistance in EGFR-mutant lung cancer via the activation of AKT and EGFR." (PMID 26989078, 2016). "EGFR-mutant lung cancer appears to be a distinct clinical entity and is primarily found in non-smokers." (PMID 27350784, 2016). "One important aspect of lung cancer-related mutant EGFR is that the protein undergoes impaired C-cbl mediated degradation stimulated by EGF." (PMID 26646697, 2016). "For the inhibitory mechanism of EGFR inhibitors and the structure similarity of ATP and tri-phosphated cordycepin, human lung cancer cell line H1975 was employed to investigate the inhibitory effect of cordycepin." (PMID 27689974, 2016). "Up to 33% of patients with EGFR-mutant lung cancer treated with EGFR TKIs will experience disease progression in the CNS." (PMID 27070580, 2016). "HLA-A2+ lung cancer cell line, H441, was chosen as target lung cancer cells as H441 expressed a detectable level of PD-L1 proteins that were down-modulated by EGFR inhibitor." (PMID 27467256, 2016). "Our group previously reported a high rate of treatment response and a better outcome in patients with WSE related lung cancer treated with EGFR-Tyrosine Kinase Inhibitors (TKIs)." (PMID 27098372, 2016).
lung cancer (continued). "Nevertheless, we confirmed that ALK-positive lung adenocarcinoma is typically solid, aggressive, and more likely to involve the local lymphatic system, compared to EGFR-positive lung cancer." (PMID 27518729, 2016). "A targeted therapy blocking oncogenic EGFR is currently the only biological anti-cancer adjuvant strategy after surgery of lung cancer." (PMID 27419630, 2016). "In this study, we characterized the clinicopathologic features and genetic changes associated with EGFR, KRAS, and ALK in lung cancer." (PMID 26992209, 2016). "The female patients smoked much less than male, and showed distinct molecular characteristics such as, higher frequency of EGFR alterations, lower frequency of KRAS mutation and distinct genetic variants in lung cancer susceptibility loci." (PMID 27009843, 2016). "Here we report that ZEB1 exerts the opposite effect in EGFR-mutated lung cancer cells, where it suppresses growth by increasing microRNA-200 targets to antagonize ERBB3, a driver of mutant EGFR-dependent cell growth." (PMID 27456471, 2016). "In conclusion, IL10 appears to have a positive effect on the formation of the tumor microenvironment via M2 macrophages as well as through the expression of EGFR in cancer cells, thereby enhancing lung cancer formation." (PMID 26956044, 2016). "Previously, it was reported that EGFR-dependent SOX2 expression or β-catenin activation by galectin-3 regulates lung cancer stem cells." (PMID 27626163, 2016). "One potential explanation is that certain EGFR mutations, which predict TKI sensitivity in lung cancer, are rare in breast cancer." (PMID 27221039, 2016). "In lung cancer, serial analysis identified emergence of activating mutations in the EFGR gene in some patients receiving EGFR-targeting therapy, conferring a mechanism of acquired resistance to therapy." (PMID 26980749, 2016). "Drug sensitivity data to EGFR inhibitor that were available for 91 out of 186 lung cancer cell lines in CCLE database were compared between PD-L1high and PD-L1low lung cancer cell lines." (PMID 27467256, 2016). "The viability of the surgically resected lung cancer was 60.0 ± 9.8 and 86.8 ± 13.9% in EGFR-mutants vs. wild types in the SDI (p = 0.0003)." (PMID 27070423, 2016). "EGFR protein is widely expressed in lung cancer tissues and most lung cancer cell lines, including H1299, A549, and H322, which were used in our experiments." (PMID 26824318, 2016). "Epidermal growth factor receptor tyrosine kinase inhibitor (EGFR-TKI) therapy is an option for lung cancers harboring wild-type EGFR when chemotherapeutic reagents have failed." (PMID 26919104, 2016). "Cell-free DNA from two lung cancer patients (LC5 and LC10) contained the classic EGFR L858R mutation." (PMID 27428049, 2016). "Epidermal growth factor receptor (EGFR) mutations and anaplastic lymphoma kinase (ALK) fusion genes represent novel oncogenes that are associated with non–small-cell lung cancers (NSCLC)." (PMID 27322143, 2016). "Epidermal growth factor receptor (EGFR)-tyrosine kinase inhibitor (TKI) readministration to lung cancer patients is common owing to the few options available." (PMID 27821111, 2016). "The specificity of anti-EGFR Ab coated CMO:Eu@GNR are used for the enabled targeting of EGFR over-expressing of human lung cancer cells (A549 cell)." (PMID 27877887, 2016). "In our study, we observed that the content of mutant EGFR DNA correlated with dCt detected by the Therascreen EGFR RGQ PCR kit (Qiagen) in lung cancer cells." (PMID 27368002, 2016). "Notch1 signaling was shown to enhance the EMT process in EGFR inhibitor resistant lung cancer cells." (PMID 26713603, 2016). "Our work thus shows that a clinical trial is warranted to determine efficacy of targeting therapy for wt-EGFR overexperssing lung cancer patients." (PMID 26646697, 2016).